CALR (calreticulin)
Diseases named in the same sentence as CALR in open-access papers (continued):
Sharing a sentence is not in itself a finding about the gene and the disease.
infection (continued). "We found significant elevations in two of these three DAMPs, calreticulin and HMGB-1, following infection of all our SS cell lines with MV-s-NAP." (PMID 41235176, 2025). "Further, these cell lines showed a significant increase of calreticulin, and TRAIL receptor 1 and 2 post infection." (PMID 38494863, 2024). "Proteins such as tryparedoxin peroxidase, elongation factor 1-alpha and 2, histones H4, H2A and H2B, calreticulin and heat shock protein 70 and 85 increased in LEVs of myoblasts (C2C12) with T. cruzi in the first 2 h of infection, but decreased after 24 h." (PMID 38424216, 2024). "At 20°C, the expression of Ciita, NFYB, NFYC, CALR, Canx and TNF reached the peak at 24 hpi, which was significantly higher and earlier compared to 10°C infection group." (PMID 35197977, 2022). "In the present study, two of these biomarkers, calreticulin (CRT) and triose phosphate isomerase (TPI), were recombinantly expressed and evaluated using experimental infection sera as candidates of a novel molecular test platform to measure TCBZ efficacy." (PMID 32751696, 2020). "Laminin binding to VP31 mediates WSSV infection and a soluble C-type lectin (MjsvCL) interacts with VP28 and calreticulin, which facilitates WSSV infection in shrimp." (PMID 30726286, 2019). "We demonstrate that infection of murine and a range of human bladder cancer cells with NDV leads to upregulation of MHC proteins, calreticulin, and induction of type I interferon-related genes." (PMID 29983890, 2018). "We have previously shown, that during ex vivo infection of HPE, T. cruzi calreticulin (TcCRT) acts as a virulence factor since it binds maternal classical complement component C1q and increases parasite infectivity." (PMID 30143027, 2018). "Calreticulin (CRT) is persistently up-regulated in brain tissues 14 and 21 days after infection with Toxoplasma cysts." (PMID 23587304, 2013). "Additionally, KD01 significantly increased the surface expression of calreticulin in both SW780 and 5637 cells at 72 h post-infection." (PMID 40283946, 2025). "Although any direct antimicrobial effects of CALR during wound healing have not been determined, CALR has been shown to play a role in mediating the immune cell response during infection." (PMID 37692787, 2023). "Immunohistochemical staining for N-terminal calreticulin did not display statistically significant differences in the number of immunolabeled cells in all investigated cultures independent of the infection state." (PMID 35682834, 2022). "However, a marked protein overexpression of ER-stress markers such as calnexin, calreticulin and CHOP/GADD 153 have been observed in Vero cell and primary rat neurons 36 h post-infection with recombinant A75/17-V CDV." (PMID 32054075, 2020). "In this study, only tapasin was upregulated in both treatment/infection groups while CALR, ERp57, and CANX were either downregulated or not differentially expressed." (PMID 31121853, 2019). "In catfish, they found both CALR and CALRL genes to be induced upon infection." (PMID 29471808, 2018). "At the same time, many targets of RKN effectors are unknown, even in the well-described M. incognita calreticulin effector Mi-CRT, which is crucial for infection by possibly altering calcium homeostasis." (PMID 30254651, 2018). "Representative blots are depicted, showing anti-V Ab staining in the latter fractions, i.e. heavier fractions, which did not align with the calreticulin Ab (∼63 kD) stained bands, after 3 h of infection." (PMID 19609450, 2009). "Furthermore, increased levels of TAP-transporters (TAP1, TAP2), MHC I components B2M and HLAs, together with the ER chaperons calreticulin (CALR) and calnexin (CALN), and aminopeptidases ERAP1 and ERAP2 indicated upregulation of MHC I dependent antigen presentation with progressing infection." (PMID 37112941, 2023).
infection (continued). "Productive infection by two additional ZIKV strains, Puerto Rico 2015 (PRVABC59) and Thailand 201326, was observed in primary HESC by a plaque forming assay (PFA) 3 days post-infection, with intracellular co-localization of the E protein and dsRNA with calreticulin and vimentin, respectively." (PMID 28281680, 2017). "Calreticulin (AALB003666-PA) (spot 8), a multifunctional protein mainly involved in directing the proper conformation of proteins, controlling the calcium level, and resisting infection, was upregulated during the parasite invasion, potentially as a consequence of mitochondrial stress signalling." (PMID 27724938, 2016). "After 24 h infection by SARS-CoV-2 (USA-WA1 strain, same as below unless specified), the ER structure marked by calreticulin was not dramatically altered." (PMID 40540531, 2025). "Remarkably, similar outcomes were observed following infection with PRRSV where the proteolytic cleavage of ATF6 does not occur, nor is there an increase in the expression of ATF6 target genes, such calnexin or calreticulin." (PMID 41157573, 2025). "Notably, we did not detect any changes in the levels of GRP94 or Calreticulin—two prominent ER chaperones—during the lytic cycle of KSHV, suggesting that the upregulation of BiP during infection is not general to all ER chaperones." (PMID 39471213, 2024). "Confocal microscopy analysis revealed that EMCV nonstructural proteins partially overlapped with the ER marker calreticulin, but not with markers of ERES, ERGIC, cis- or trans-Golgi network, which appeared dispersed in infected cells, even at the earliest stages of infection." (PMID 26406250, 2015).
hematologic disorder (13 papers, 2016 to 2026). A disease involving the hematopoietic system. "CALR mutation detection should be reserved for patients with high suspicion of clonal haematological disease." (PMID 31882869, 2019). "Finally, CALR mutation detection should be reserved for patients with high suspicion of clonal haematological disease." (PMID 31882869, 2019). "The curated SNPs and disease association database reports that somatic CALR SNP variants are present in patients with at least 20 different types of hematologic malignancies and solid cancers, suggesting that they increase the susceptibility of normal cells to develop driver mutations." (PMID 29218307, 2017). "Given the prevalence of underlying hematological disorders, it is essential to investigate somatic mutations in the JAK2, including V617F and exon 12 mutations, as well as mutations in the CALR and MPL genes." (PMID 40242703, 2025). "NGS covering 51 genes related to hematological malignancies revealed NRAS-p.Gly12Asp, PTPN11-p.Asp61Val, PTPN11-p.Thr468Met, KRAS-p.Gly12Val, and CALR-p.Gly108Arg mutations." (PMID 35912172, 2022). "Moreover, there are reports that the expression of CALR is remarkably higher than other hematologic malignancies, such as ambiguous lineage, ALL, MPN, MDS/MPN." (PMID 34025649, 2021). "In our study, we assumed that our patient did not develop a CALR mutation that would imply a clonal haematological disease." (PMID 31882869, 2019). "Philadelphia-negative myeloproliferative neoplasms (Ph-MPNs) are clonal hematologic malignancies characterized not only by driver mutations such as JAK2V617F, CALR, and MPL but also by a profoundly dysregulated immune microenvironment." (PMID 40944087, 2025). "Our data suggest that GRP78, CALR, PDIA3 and GPI released from irradiated MSC act as mediators of genetic instability in human CD34+ cells with potential implications for radiation-induced hematologic disorders." (PMID 35740549, 2022).
blood cancer (5 papers, 2022 to 2024). "This remarkable case provides definitive evidence of a very early developmental origin of CALR-mutant blood cancer, presenting in adults as overt disease decades later." (PMID 35637336, 2022).
cardiovascular diseases (5 papers, 2013 to 2023). "The present study identified Pitx2 as a prioritized gene network hub, i.e. specific promotion of Pitx2 in Cardiovascular Disease development was observed under conditions of CALR truncation/deficiency." (PMID 26179794, 2015).
cardiac disease (4 papers, 2015 to 2024). "Specific promotion of Pitx2 in cardiac disease development under conditions of CALR deficiency suggests its critical involvement within the CALR-regulated cardiogenic network." (PMID 26179794, 2015). "Given the known association between excessive cardiac calreticulin expression and impaired cardiac function, upregulation of cardiac calreticulin may increase the risk of adult heart disease due to prenatal overexposure to GCs." (PMID 39351527, 2024). "The discovery that calreticulin induces apoptotic signaling while simultaneously protecting cardiac cells from cell death when overexpressed or severely downregulated may shed light on the mechanisms driving these and other cardiac diseases as well." (PMID 32323496, 2020).
bacterial infection (3 papers, 2012 to 2025). "Recently, the coordinated up-regulation of MHC class I-related components including MHC class I alpha chain, β2m, calreticulin, endoplasmin, PA28α and PA28β were reported in large yellow croaker following poly I:C injection and in catfish following an intracellular bacterial infection." (PMID 22805612, 2012).
hematological cancers (3 papers, 2016 to 2023). "Of interest, mutations in CALR C-terminus are also observed in a variety of non-hematological cancers and their exposure at the cell surface leads to immunosuppressive activity." (PMID 37019903, 2023). "To investigate whether CALR mutations were present in other hematopoietic neoplasms, we screened 135 patients with AML and 57 patients with ALL." (PMID 26377485, 2016).
kidney disease (3 papers, 2013 to 2018). "Specifically, we found substantial additional evidence for a role of calreticulin in renal disease in humans by showing that calreticulin is involved in a larger interaction network in renal graft rejection." (PMID 23883183, 2013). "Calreticulin is a protein involved in renal disease in animals." (PMID 23883183, 2013).
neurological disorders (3 papers, 2017 to 2022). "Another member of this group is the ER chaperone CALR, which has multiple functions including the regulation of Ca2+ homeostasis and protein folding, and was found dysregulated in neurological disorders, including ALS." (PMID 35164882, 2022).
inflammatory myopathies (2 papers, 2010 to 2013). "The aim of the present study was therefore to investigate the stress-response ongoing in muscle fibers of patients affected with inflammatory myopathies, focusing on Grp94, calreticulin and Grp75 expression and distribution." (PMID 20334640, 2010). "The present study was undertaken to characterize in more detail the ER stress-response occurring in myofibers of patients with inflammatory myopathies, focusing on the expression and distribution of Grp94, calreticulin and Grp75, three ER chaperones involved in immunomodulation." (PMID 20334640, 2010). "Four molecular chaperones, glucose-regulated protein 94 (GRP94), glucose-regulated protein 78 (GRP78), calreticulin and calnexin and valosin containing protein (VCP) were highly expressed in GNE myopathy." (PMID 23472144, 2013).
lung (2 papers, 2020 to 2022). "For instance, CALR blockade alleviated acute lung injury (ALI), reduced pro-inflammatory cytokine expression, and inhibited neutrophil and T cell infiltration in bronchoalveolar lavage and lung tissues in lipopolysaccharide (LPS)-induced ALI mouse model." (PMID 36387401, 2022).
connective tissue diseases (1 paper, 2022). "Calreticulin is an autoantigen in RA and other connective tissue diseases." (PMID 35027076, 2022).
neurodegenerative disease (1 paper, 2019). A disorder of the central nervous system characterized by gradual and progressive loss of neural tissue and neurologic function. "Because such a strategy has shown benefits in neurodegenerative diseases, modulating the degradation of CALR mutant proteins by the ERAD-proteasome pathway might represent an appealing strategy to improve the management of CALR-mutated MPN." (PMID 31810292, 2019).
CALR also shares sentences with these, for which no sentence is quoted: esophageal squamous cell carcinoma (5 papers); acute leukemia (4); lung squamous cell carcinoma (4); lupus (4); multiple myeloma (3); Thrombocytopenia (3); type 2 diabetes mellitus (3); acute coronary syndrome (2); acute T-cell leukemia (2); alopecia (2); bone marrow failure (2); cardiac ischemia (2); chronic eosinophilic leukemia (2); chronic myelomonocytic leukemia (2); diffuse large B-cell lymphoma (2); encephalitis (2); inflammatory bowel disease (2); lymphoid neoplasm (2); malaria (2); metabolic disorders (2); monoclonal gammopathy (2); prostate tumor (2); acute megakaryoblastic leukemia (1); acute panmyelosis (1); Acute promyelocyte leukemia (1); acute respiratory distress syndrome (1); adrenocortical carcinomas (1); Airway obstruction (1); aortic stenosis (1); arterial hypertension (1).
A further 79 diseases each share a sentence with CALR in 1 paper.